ZNF627 (zinc finger protein 627)
Description:
May be involved in transcriptional regulation.
Synonyms: FLJ90365
Tractability: PROTAC: UniProt records ubiquitination sites on it; ubiquitination databases record sites on it.
Gene: Protein-coding gene on chromosome 19 (11,559,374 to 11,619,161, forward strand). Ensembl gene ENSG00000198551.
Subcellular location: Nucleus
Subcellular location (Human Protein Atlas): Nucleoplasm; Nucleoli
Pathways (Reactome):
Gene expression (Transcription): Generic Transcription Pathway
Gene Ontology:
Molecular function: protein binding; DNA-binding transcription factor activity, RNA polymerase II-specific; RNA polymerase II transcription regulatory region sequence-specific DNA binding
Biological process: regulation of transcription by RNA polymerase II; regulation of DNA-templated transcription
Cellular component: nucleus
Genetic constraint (gnomAD): Loss-of-function variants: 13 observed, 11.08 expected, observed/expected ratio (o/e) 1.17, 90% interval 0.76 to 1.78. The upper end of that interval is the gene's LOEUF score, 1.78, which puts it in group 6 of 6, group 1 being the genes least tolerant of losing a copy. Missense variants: 504 observed, 593.76 expected, observed/expected ratio (o/e) 0.85, 90% interval 0.79 to 0.91. Synonymous variants: 176 observed, 193.87 expected, observed/expected ratio (o/e) 0.91, 90% interval 0.8 to 1.03.
Homologues: Orthologues: chimpanzee ZNF627 (99% identical), mouse Zfp872 (61% identical). Paralogues in human: ZNF136 (69% identical), ZNF670 (52% identical), ZNF625 (51% identical), ZNF426 (44% identical), ZNF527 (44% identical), ZNF285 (41% identical), ZNF852 (41% identical), ZKSCAN7 (40% identical), ZNF287 (40% identical), ZNF34 (40% identical), ZNF214 (39% identical), ZNF17 (38% identical), and 38 more.
Diseases named in the same sentence as ZNF627 in open-access papers:
ZNF627 is named in the same sentence as 1 disease in open-access papers, as found by Europe PMC text mining. Sharing a sentence is not in itself a finding about the gene and the disease.
dementia (1 paper, 2024). Loss of intellectual abilities interfering with an individual's social and occupational functions.